ALB (albumin)
Diseases named in the same sentence as ALB in open-access papers (continued):
Sharing a sentence is not in itself a finding about the gene and the disease.
malnutrition (continued). "Albumin, as an indicator of malnutrition in clinically stable conditions, was recorded within normal ranges." (PMID 41345186, 2025). "The level of endogenous serum albumin in the body can be reduced in many illnesses such as malnutrition, liver diseases, cancers, trauma and nephrotic syndrome due to decreased synthesis, excessive excretion and/or enhanced vascular permeability." (PMID 40656900, 2025). "High ABLI grade consisted of high bilirubin and low albumin levels represent significant poor liver functions, malnutrition and immunosuppression." (PMID 40334215, 2025). "A decrease in albumin levels indicates systemic inflammation, malnutrition, or liver and kidney dysfunction." (PMID 40783688, 2025). "Protein-calorie malnutrition is attributed to poor nutritional intake and inflammation suppress albumin synthesis." (PMID 40004975, 2025). "From a clinical perspective, low ALB levels should prompt physicians to consider the possibility of malnutrition and, consequently, lower VD levels." (PMID 40313432, 2025). "Reduced albumin levels are often indicative of malnutrition, liver dysfunction, or chronic diseases." (PMID 40568468, 2025). "The albumin level, an important indicator of malnutrition assessment, also shows a clear upward trend on the graph, with the average level increasing from 2.94 g/dL in the first month of hospitalization to an average of 3.8 g/dL by the last month." (PMID 40760640, 2025). "Serum albumin (Alb), a widely used biomarker for nutritional assessment, is often reduced in patients with malnutrition." (PMID 41496912, 2025). "Serum albumin is a key biomarker of nutritional status, with reduced levels commonly observed in patients with malnutrition." (PMID 41156445, 2025). "Considering these current data, an optimization process should be initiated with preoperative support in the presence of low albumin and screening-detected malnutrition, in addition to prognostic indices such as PNI." (PMID 41373357, 2025). "Despite previousliterature suggesting a link between sarcopenia, malnutrition and chemotherapy-induced peripheral neuropathy (CIPN), our study found nosignificant association between L3 SMI, albumin, vitamin B12 and neuropathy." (PMID 41393484, 2025). "Of the two binary malnutrition indicators, less than 1% had serum albumin below 35 g/dL, whereas 8% had Body Mass Index (BMI) < 21 kg/m2." (PMID 40979196, 2025). "As a result, materials like albumin are lost from blood vessels into the interstitial fluid, aggravating the body’s malnutrition state and promoting the development of tumors." (PMID 41142623, 2025). "Both albumin and creatinine are known to be markers for malnutrition and lower muscle mass, as well as key components of the systemic inflammatory response that affects cardiac functions and overall survival after cardiomyocyte injury." (PMID 40095884, 2025). "Hypoalbuminemia is a common characteristic of severe malnutrition and is characterized by a decrease in the level of albumin in plasma, which in turn increases the Vd of some drugs, such as VPA." (PMID 40872507, 2025). "In this study, an elevated erythrocyte sedimentation rate (ESR) and low albumin levels were also linked to PC19-PF, indicating both systemic inflammation and possible nutritional deficiency." (PMID 40872813, 2025). "Laboratory blood tests, including hemoglobin as a marker of anemia, lymphocyte count, albumin, and glucose, are widely used in the assessment of patients with malnutrition." (PMID 38610609, 2024). "Low serum albumin is not only a marker of malnutrition but is also considered a biomarker of systemic inflammation, a view strongly supported by previous research." (PMID 38966640, 2024). "Clinical variables such as body mass index, comorbidities, malnutrition inflammation, quality of life, fasting glycemia, glycosylated hemoglobin, hematocrit, uremia, creatinine, sodium, calcium, potassium, albumin, ferritin, C reactive protein were measured." (PMID 39723266, 2024).
malnutrition (continued). "The association between malnutrition and cognitive function is unclear, but the GNRI validated the use of serum albumin and weight reduction in this examination to explore the connection instead of relying solely on a solitary biomarker." (PMID 39624685, 2024). "Patients with preoperative malnutrition, as indicated by serum albumin levels below 35g/l, exhibited a higher proportion of major complications (p = 0.022), but anemia was not predictive of postoperative morbidity." (PMID 39604574, 2024). "The Geriatric Nutritional Risk Index (GNRI), which is calculated using body mass index (BMI) and serum albumin, has been developed to define malnutrition." (PMID 38997737, 2024). "Prealbumin (PAB), synthesized by liver cells, is more sensitive to malnutrition compared to albumin and transferrin due to its half-life of only 12 h." (PMID 39234292, 2024). "The level of serum albumin and TP remains normal for a long time, and laboratory indicators deteriorate in the state of advanced malnutrition." (PMID 38999890, 2024). "Like malnutrition, hypoalbuminaemia is also prognostic of poor outcomes, including mortality; but it is important to dissociate them since many patients with malnutrition have a normal albumin." (PMID 39658522, 2024). "Future research can utilize albumin as a medium to explore the connections among aging, malnutrition, and macrophages, thereby exploring the immune mechanism in greater depth." (PMID 39351234, 2024). "In relation to nutrition, malnutrition, high Body Mass Index (BMI), frailty, sarcopenia, serum albumin and folic acid level, osteoporotic treatment, and low hemoglobin levels are also crucial predictors." (PMID 39519455, 2024). "These include elevated CRP levels, low serum albumin levels, hypernatremia, advanced age, malnutrition, comorbidities, and advanced stages of cancer." (PMID 38463403, 2024). "New criteria for diagnosing malnutrition in the elderly aim to boost precision beyond traditional methods like BMI and serum albumin levels." (PMID 39125381, 2024). "Decreased serum albumin concentration is a characteristic change of malnutrition, but due to the long half-life of albumin, mild to moderate malnutrition changes little, and the sensitivity is not high." (PMID 39876914, 2024). "Nevertheless, low serum albumin levels are generally found in hospitalized patients and patients with malnutrition or cachexia (e.g., due to disease progression)." (PMID 38550297, 2024). "The predictive value of serum GDF15, albumin (ALB), and a combination of these was evaluated to identify malnutrition in patients with AECOPD using a receiver operating characteristic (ROC) curve." (PMID 39050134, 2024). "Several different malnutrition markers like serum albumin, muscle mass, body mass index, Mini-Nutritional Assessment Short-Form, Subjective Global Assessment, PNI, CONUT, GNRI, etc., have been reported in the literature." (PMID 38735935, 2024). "Vitamin D deficiency was present in 79.7% of patients, and a high prevalence of malnutrition was indicated by low albumin and elevated BUN levels." (PMID 39519455, 2024). "In this study, we separately analyzed the predictive efficacy of serum GDF-15 and albumin levels in patients with malnutrition and AECOPD." (PMID 39050134, 2024). "An SR emphasized that albumin, although widely used as a nutritional biomarker, can be influenced by factors beyond malnutrition, including inflammation, hydration, and liver function." (PMID 39771008, 2024). "Our findings further support the notion that decreased levels of RBC, HGB, ALB, and PAB are associated with an increased risk of malnutrition." (PMID 39664913, 2024). "Preoperative serum albumin is a useful marker for detecting malnutrition and predicting outcomes, with early intervention in hypoalbuminemia potentially reducing complications." (PMID 39683394, 2024).
malnutrition (continued). "Recently, the controlling nutritional status (CONUT) score has emerged as a promising tool for assessing malnutrition in hospitalized patients, incorporating serum albumin, lymphocyte count, and total cholesterol levels." (PMID 39044162, 2024). "Biochemical markers commonly used to assess malnutrition in the elderly include serum albumin, prealbumin, transferrin, and retinol-binding protein." (PMID 39125381, 2024). "The HALP score combines malnutrition factors (hemoglobin and albumin) with inflammatory response factors (lymphocyte and platelet counts)." (PMID 39744624, 2024). "At post-hoc analysis, patients with moderate/severe malnutrition were significantly older than the other groups as well showed lower haemoglobin, lymphocytes, albumin, total cholesterol, LDL, and HDL values." (PMID 38474705, 2024). "Numerous studies have highlighted that low albumin levels can indicate poor prognosis and malnutrition." (PMID 39768386, 2024). "Hypoalbuminemia (serum albumin < 35 g/L), a manifestation of malnutrition commonly observed in elderly hip fracture patients, is intrinsically associated with postoperative complications and premature mortality." (PMID 39076765, 2024). "Several studies have identified BMI, hemoglobin (HGB), total cholesterol (TC), albumin (ALB), and serum leptin as biomarkers associated with malnutrition in older individuals." (PMID 38622502, 2024). "Albumin is commonly employed to evaluate malnutrition, particularly in chronic kidney disease patients undergoing dialysis." (PMID 38874108, 2024). "Studies have reported that in the later stages of the disease, malnutrition and inflammation inhibit albumin synthesis, resulting in lower serum albumin concentrations." (PMID 39744624, 2024). "Malnutrition identified using the simplified GLIM criteria is associated with age, CDAI, behavior, hemoglobin, and albumin, providing prognostic value for endoscopic remission in CD patients." (PMID 39850334, 2024). "In first instance, low muscle density and ADS are both parameters reflecting malnutrition and low serum albumin level." (PMID 39614916, 2024). "Lymphocytes are more prominent in chronic inflammation, and albumin levels are also at the forefront in malnutrition and chronic inflammation." (PMID 38802494, 2024). "In summary, elevated CRP levels and WBC counts reflect an inflammatory response that can promote tumor growth and metastasis, while low albumin levels indicate malnutrition and chronic inflammation." (PMID 39513125, 2024). "The prevalence of malnutrition was 43.8% using the 7-point SGA assessment, and malnutrition was independently associated with lower serum albumin, creatinine, MUAC, BCM and unemployment." (PMID 38866974, 2024). "Low albumin levels are considered as an indicator of malnutrition, while obesity is usually considered as overnutrition." (PMID 39287227, 2024). "Most of our population had higher AJCC stages III and IV (69.2%), while malnutrition based on albumin <3.5 g/dL and low haemoglobin <11 g/dL was found in 40% and 44.4% of the patients, respectively." (PMID 38774568, 2024). "For that reason, it is also conceivable that decrements of serum albumin concentration were also favored by a catabolic state or the combined presence of malnutrition and inflammation." (PMID 39834917, 2024). "Reduced ALB levels signify chronic or severe malnutrition and inflammation, often correlating with unfavorable prognoses and outcomes." (PMID 39839282, 2024). "Malnutrition, particularly reduced albumin levels, leads to decreased healing substrates, delaying the healing process." (PMID 38929357, 2024). "Albumin <35 g/L indicates hypoalbuminemia and persistent hypoalbuminemia is an important indicator of malnutrition." (PMID 38832098, 2024). "Serum albumin is an important marker of host nutritional status and is closely correlated with the degree of malnutrition." (PMID 38347528, 2024).
malnutrition (continued). "Malnutrition and inflammatory processes suppress albumin synthesis over time, contributing to tumor cachexia." (PMID 39400724, 2024). "The multivariable analysis showed a significantly higher risk of malnutrition in patients with stage 3 disease according to the ISS classification (OR = 3.39) and lower albumin levels (OR = 4.56; p = 0.0125)." (PMID 38610941, 2024). "AGR combines the advantages of albumin and globulin, and its imbalance indicates the presence of infection, malnutrition, chronic systemic inflammation, liver function impairment, or autoimmune issues." (PMID 39421614, 2024). "The ROC analysis identified albumin, leptin, myostatin, and adiponectin as biomarkers of malnutrition diagnosed using the 7-Point SGA." (PMID 39125361, 2024). "Serum albumin serves as a pivotal indicator of nutritional status, that is closely correlated with degree of malnutrition, and routinely applied in clinical settings to assess and monitor nutritional health." (PMID 39624689, 2024). "Albumin is an indicator of nutritional status, which is reduced in case of severe malnutrition, chronic inflammation, and autoimmune diseases." (PMID 38886765, 2024). "Adequate nutrition is essential for tissue remodeling, and low serum albumin is a marker of malnutrition." (PMID 39119009, 2024). "Malnutrition is often accompanied by decreased protein synthesis, as indicated by decreased serum albumin (ALB) and prealbumin (PAB) levels." (PMID 39519547, 2024). "Subsequently, serum albumin and transferrin became highly utilized markers of malnutrition for hospitalized patients." (PMID 38379550, 2024). "Lastly, chronic inflammation and malnutrition have an impact on the synthesis of albumin, which serves as a robust indicator of the onset of CVD in various patient populations." (PMID 39044162, 2024). "Accordingly, lower levels of serum albumin, an indicator of malnutrition, were significantly more frequently noted in patients with a decreased MD compliance (p = 0.0012)." (PMID 38392632, 2024). "Decreased albumin concentrations in the course of cancer usually indicate malnutrition and cachexia." (PMID 39464717, 2024). "Some studies have reported malnutrition using body mass index (BMI), albumin serum levels, skin fold thickness or their combination." (PMID 39447215, 2024). "According to recent studies, low serum albumin levels are common in patients with heart failure (25–33%) due to several factors including lifestyle, absorption disorders, a complex malnutrition–inflammation syndrome, which produces excessive oxidative stress." (PMID 38999889, 2024). "In this study, we also identified a significant correlation of BMI with serum albumin, a widely used laboratory parameter for indices for malnutrition, because of its long half-life." (PMID 38496132, 2024). "Serum albumin level serves as a key factor in defining cancer cachexia and cancer-related malnutrition." (PMID 38438901, 2024). "A Decreased serum albumin concentration usually reflects malnutrition in cancer patients, predictive of a poor cancer prognosis." (PMID 39568563, 2024). "The meta‐analysis results indicate that the malnutrition group had significantly lower BMI, ALB, and Hb values compared with the normal nutrition group." (PMID 39364802, 2024). "Albumin is a well-established marker of malnutrition that was analyzed in five of the studies in this literature review." (PMID 39518692, 2024). "Acute toxic effects can lead to changes in serum levels of albumin, glucose, or total cholesterol, indicating serious adverse conditions, including liver dysfunction, malnutrition, systemic inflammation, or alterations in carbohydrate and lipid metabolism." (PMID 39595140, 2024). "Malnutrition (serum albumin < 35 g/L) negatively affected wound healing, and these patients were more susceptible to deep infections." (PMID 39261893, 2024).
malnutrition (continued). "The high predictive value of the GNRI can be attributed to its incorporation of two important markers of malnutrition: albumin and body weight." (PMID 38997737, 2024). "CRP is also a marker of acute-phase inflammatory response, and low level of albumin indicates malnutrition as well as inflammation severity and disease progression." (PMID 38649407, 2024). "Decreased serum albumin expression has been recognized as a marker of malnutrition and a weak immune defense system, and its substantial reduction frequently serves as a warning sign of postoperative complications for clinicians." (PMID 38877445, 2024). "ROC analysis showed that serum GDF-15 levels had a lower sensitivity than serum albumin, but a higher specificity in predicting malnutrition in patients with AECOPD." (PMID 39050134, 2024). "The utility of using low serum albumin and low pre-albumin as a rationale for diagnosing malnutrition has been questioned in recent years." (PMID 39308920, 2024). "Serum PAB and ALB levels are regarded as nutritional markers reflecting short- and long-term malnutrition, respectively." (PMID 39519547, 2024). "Long-term nutritional consumption is very easy to lead to malnutrition and decreased albumin levels." (PMID 38579053, 2024). "Regarding the analytical parameters of malnutrition, an average of absolute lymphocyte of 1758 cel/mm3, cholesterol of 162.9 mg/dL, and albumin of 3.7 g/dL indicated mild malnutrition." (PMID 39599649, 2024). "Research assessing malnutrition risk in IPF patients, based on serum albumin levels, body weight, and ideal body weight, found that this risk is an independent prognostic factor." (PMID 39407934, 2024). "Thirdly, our study demonstrated that malnutrition risk is associated with profound metabolic disturbances, as evidenced by elevated NLR, increased INR, and decreased levels of albumin, total protein, and cholesterol at admission." (PMID 39125277, 2024). "In the literature, it was reported that serum albumin levels decreased in COPD as a result of malnutrition and increased inflammatory response." (PMID 38674175, 2024). "Serum-albumin is being used to determine the nutritional status since malnutrition and chronic systemic inflammation in cancer affect albumin synthesis." (PMID 39400724, 2024). "Although diminished levels of albumin serve as an indicator of malnutrition, they concurrently function as a biomarker for systemic inflammation." (PMID 38589844, 2024). "Albumin is a classic marker for assessing malnutrition; however, its concentration is influenced not only by protein intake but also by factors such as overhydration, inflammation, or other physiological disturbances." (PMID 39834734, 2024). "In our population, malnutrition determined by low albumin levels was the most important predictor of DA, this complication occurred 22.2 more times in these patients." (PMID 38774568, 2024). "We also observed malnutrition in 28.1% of our cases and low albumin levels adversely affected our cohort, as demonstrated in the univariate analysis." (PMID 38672542, 2024). "Serum albumin and total cholesterol are effective indicators to evaluate the nutritional status of the body, and the decrease in their levels reflects malnutrition." (PMID 38562035, 2024). "Recent research has indicated that low albumin levels often signify malnutrition, which can impair immune response, reduce lung muscle strength, and diminish respiratory function, thereby accelerating COPD progression." (PMID 39737157, 2024). "The presence of malnutrition status and sarcopenia is also supported by lower values of proteins as well as of serum albumin and CPK and by a chronic status of inflammation, expressed by a significant increment in CRP and neutrophil values." (PMID 38786972, 2024).